GNG8 (G protein subunit gamma 8)
Description:
Guanine nucleotide-binding proteins (G proteins) are involved as a modulator or transducer in various transmembrane signaling systems. The beta and gamma chains are required for the GTPase activity, for replacement of GDP by GTP, and for G protein-effector interaction.
Synonyms: HG3E
Tractability: Antibody: UniProt places it where antibodies can reach, with high confidence; its Gene Ontology location is reachable by antibodies, with high confidence.
Gene: Protein-coding gene on chromosome 19 (46,633,953 to 46,636,649, reverse strand). Ensembl gene ENSG00000167414.
Subcellular location: Cell membrane
Pathways (Reactome):
Signal Transduction: Ca2+ pathway; Extra-nuclear estrogen signaling; G alpha (12/13) signalling events; G alpha (i) signalling events; G alpha (q) signalling events; G alpha (s) signalling events; G alpha (z) signalling events; G beta:gamma signalling through BTK; G beta:gamma signalling through CDC42; G beta:gamma signalling through PI3Kgamma; G beta:gamma signalling through PLC beta; G-protein activation; GPER1 signaling; Glucagon-type ligand receptors
Hemostasis: ADP signalling through P2Y purinoceptor 1; ADP signalling through P2Y purinoceptor 12; Prostacyclin signalling through prostacyclin receptor; Thrombin signalling through proteinase activated receptors (PARs); Thromboxane signalling through TP receptor
Metabolism: Adrenaline,noradrenaline inhibits insulin secretion; Glucagon signaling in metabolic regulation; Glucagon-like Peptide-1 (GLP1) regulates insulin secretion
Neuronal System: Activation of G protein gated Potassium channels; Inhibition of voltage gated Ca2+ channels via Gbeta/gamma subunits; Presynaptic function of Kainate receptors
Cellular responses to stimuli: High laminar flow shear stress activates signaling by PIEZO1 and PECAM1:CDH5:KDR in endothelial cells
Disease: ADORA2B mediated anti-inflammatory cytokines production
Metabolism of proteins: Cooperation of PDCL (PhLP1) and TRiC/CCT in G-protein beta folding
Transport of small molecules: Vasopressin regulates renal water homeostasis via Aquaporins
Gene Ontology:
Molecular function: protein binding; G-protein beta-subunit binding; GTPase activity
Biological process: G protein-coupled receptor signaling pathway; nervous system development
Cellular component: heterotrimeric G-protein complex; plasma membrane
Genetic constraint (gnomAD): Loss-of-function variants: 5 observed, 5.83 expected, observed/expected ratio (o/e) 0.86, 90% interval 0.44 to 1.69. That is too few expected variants to judge how well the gene tolerates losing a copy. Missense variants: 88 observed, 102.11 expected, observed/expected ratio (o/e) 0.86, 90% interval 0.72 to 1.03. Synonymous variants: 32 observed, 42.89 expected, observed/expected ratio (o/e) 0.75, 90% interval 0.56 to 1.
Homologues: Orthologues: chimpanzee GNG8 (100% identical), rabbit GNG8 (100% identical), dog GNG8 (99% identical), guinea pig GNG8 (99% identical), mouse Gng8 (99% identical), pig GNG8 (99% identical), rat Gng8 (99% identical), zebrafish gng8 (80% identical), tropical clawed frog dact3 (66% identical). Paralogues in human: GNG2 (70% identical), GNG4 (60% identical), GNG3 (56% identical), GNG7 (51% identical), GNG12 (49% identical), GNG10 (46% identical), GNG5 (43% identical), GNG5B (41% identical), GNGT2 (33% identical), GNGT1 (31% identical), GNG11 (30% identical).
Diseases named in the same sentence as GNG8 in open-access papers:
GNG8 is named in the same sentence as 8 diseases in open-access papers, as found by Europe PMC text mining. Sharing a sentence is not in itself a finding about the gene and the disease. The quoted sentences say what the papers report.
Intellectual disability (1 paper, 2022). "Given the location of Gng8 within 19q13.32 from where deletions have been associated with intellectual disability, the question arises as to whether Gng8 has any role in regulating cognitive function." (PMID 35115702, 2022).
small lymphocytic lymphoma (1 paper, 2021). "The recurrence of sporadic chronic lymphocytic leukemia (CLL) and small lymphocytic lymphoma (SLL) may be related to the signaling pathways of certain G proteins (including GNG8) and G protein-coupled receptors." (PMID 34322156, 2021).
tumor (4 papers, 2020 to 2025). "The expression of GNG8, MYO1H, and TNFRSF13B was significantly down-regulated, while the expression of SYT14 and FOXA2 was significantly up-regulated in the samples with higher tumor stage, the samples with high risk had lower overall survival rates." (PMID 34322156, 2021). "Moreover, the expression of GNG8, MYO1H, and TNFRSF13B was significantly down-regulated, while the expression of SYT14 and FOXA2 was significantly up-regulated in the samples with higher tumor stage." (PMID 34322156, 2021).
cancer (2 papers, 2016 to 2021). A tumor composed of atypical neoplastic, often pleomorphic cells that invade other tissues. "However, the functions of TRAV34, GTSF1L, LILRA4, and GNG8 in carcinoma remain unclear." (PMID 34844217, 2021).
GNG8 also shares sentences with these, for which no sentence is quoted: cervical cancer (1 paper); cognitive deficits (1); glioma (1); liver cancer (1).